CPT1B (carnitine palmitoyltransferase 1B)
Diseases named in the same sentence as CPT1B in open-access papers (continued):
Sharing a sentence is not in itself a finding about the gene and the disease.
CPT1B also shares sentences with these, for which no sentence is quoted: anaphylaxis (6 papers); food allergy (6); parasitemia (6); Allergy (5); type 2 diabetes (5); asthma (3); bacteremia (2); Glucose intolerance (2); hyperlipidemia (2); lipid metabolic disorders (2); adenocarcinoma (1); atopic dermatitis (1); Atrophy (1); attention deficit-hyperactivity disorder (1); Cachexia (1); chronic lymphocytic leukemia (1); conjunctivitis (1); dengue disease (1); diabetic nephropathy (1); eosinophilia (1); gastric cancer (1); glioblastoma (1); heart diseases (1); hyperglycaemia (1); intrahepatic cholestasis (1); keratoconus (1); leukemia (1); lymph node metastasis (1); melanoma (1); Neonatal sepsis (1).
A further 6 diseases each share a sentence with CPT1B in 1 paper.